TP53I11 (tumor protein p53 inducible protein 11)
Synonyms: PIG11
Tractability: Antibody: UniProt predicts a signal peptide or a membrane-spanning region. PROTAC: ubiquitination databases record sites on it; its protein half-life has been measured.
Gene: Protein-coding gene on chromosome 11 (44,885,903 to 44,951,306, reverse strand). Ensembl gene ENSG00000175274.
Subcellular location: Membrane
Subcellular location (Human Protein Atlas): Endoplasmic reticulum; Golgi apparatus; Acrosome; Principal piece
Gene Ontology:
Biological process: negative regulation of cell population proliferation
Cellular component: membrane
Genetic constraint (gnomAD): Loss-of-function variants: 7 observed, 20.07 expected, observed/expected ratio (o/e) 0.35, 90% interval 0.2 to 0.65. The upper end of that interval is the gene's LOEUF score, 0.65, which puts it in group 2 of 6, group 1 being the genes least tolerant of losing a copy. Missense variants: 169 observed, 248.27 expected, observed/expected ratio (o/e) 0.68, 90% interval 0.6 to 0.77. Synonymous variants: 99 observed, 105.83 expected, observed/expected ratio (o/e) 0.94, 90% interval 0.79 to 1.11.
Homologues: Orthologues: dog TP53I11 (95% identical), guinea pig TP53I11 (95% identical), rabbit TP53I11 (93% identical), rat Tp53i11 (92% identical), mouse Trp53i11 (90% identical), pig TP53I11 (90% identical), tropical clawed frog tp53i11 (75% identical), zebrafish tp53i11b (69% identical), zebrafish tp53i11a (67% identical), chimpanzee TP53I11 (65% identical), macaque TP53I11 (62% identical), Caenorhabditis elegans Y9C12A.1 (28% identical).
Diseases named in the same sentence as TP53I11 in open-access papers:
TP53I11 is named in the same sentence as 13 diseases in open-access papers, as found by Europe PMC text mining. Sharing a sentence is not in itself a finding about the gene and the disease. The quoted sentences say what the papers report.
breast carcinoma (3 papers, 2016 to 2024). "A pan-cancer analysis showed that high TP53I11 expression was significantly associated with poor overall survival in breast cancer." (PMID 39770537, 2024). "Beyond breast cancer, TP53I11 also exhibits tumor-suppressive effects in hepatocellular carcinoma (HCC), where its downregulation correlates with increased cell proliferation and poor prognosis." (PMID 39795889, 2024). "Our statistical analysis revealed a significant upregulation of TP53I11 expression in breast cancer tissues from DOX-treated patients compared to untreated controls, regardless of whether DOX was administered in combination or sequentially with cyclophosphamide." (PMID 39795889, 2024).
hepatocellular carcinoma (3 papers, 2011 to 2024). A malignant tumor that arises from hepatocytes. "TP53I11 associated with cytarabine AUC and overexpression of the gene promotes apoptosis in hepatocellular carcinoma cells." (PMID 21755009, 2011). "Similarly, overexpressed TP53I11 induced apoptosis in human hepatocellular carcinoma HepG2 cells." (PMID 39770537, 2024).
melanoma (2 papers, 2016 to 2021). A malignant, usually aggressive tumor composed of atypical, neoplastic melanocytes.
gastric cancer (1 paper, 2024). A primary or metastatic malignant neoplasm involving the stomach. "However, in gastric cancer, high TP53I11 expression is associated with poor prognosis, indicating that the tumor-suppressive or tumor-promoting role of TP53I11 may be tissue specific." (PMID 39795889, 2024).
metastatic tumors (1 paper, 2021). "DIRAS1, FBXL16, TP53I11, TFF2, and ZNF467 were upregulated in both metastatic tumors and GHSROS-overexpressing PC3 and LNCaP cells, while AASS, CHRDL1, CNTN1, IFI16, and MUM1L1 were downregulated." (PMID 33585078, 2021).
preeclampsia (1 paper, 2023). Preeclampsia is a hypertensive disorder of pregnancy that is characterized by new-onset hypertension with proteinuria presenting after 20 weeks of gestation, and depending on mild or severe forms may initially present with severe headache, visual disturbances, and hyperreflexia. "TP53I11 and TP53AIPI have also been shown to regulate homeostasis when the cells are in a state of stress and shown to be involved in preeclampsia." (PMID 37854252, 2023).
Sertoli Cell-Only Syndrome (1 paper, 2025). A type of male infertility in which no germ cells are visible in any of the biopsied SEMINIFEROUS TUBULES (type I) or in which germ cells are present in a minority of tubules (type II). "TP53I11 and EDDM3B were also associated with Sertoli cell-only syndrome and TEX101, EDDM3B, and PLCZ1 with varicocele." (PMID 40497989, 2025).
ulcerative colitis (1 paper, 2016). An inflammatory bowel disease involving the mucosal surface of the large intestine and rectum. "Five (42%) of the associated genes with these CpG sites have been linked to either ulcerative colitis (FLT1 and ELTD1) or CRC (PCDHG4A, GJD2, and TP53I11)." (PMID 27006956, 2016).
tumor (10 papers, 2010 to 2025). "Although a high ratio and related gene signatures associate with poor outcomes, only tumour stage and select gene expressions like TP53I11 are independently predictive, indicating that the WWOX/HIF1A axis functions within a broader context of subtype-specific risk factors." (PMID 41007296, 2025). "In luminal B tumours, our analyses show genes such as TP53I11 and RAD51 correlate with better prognosis through enhanced apoptosis and homologous recombination repair (HRR), respectively." (PMID 41007296, 2025). "Through RNAseq and Ca2+ imaging, we identified that these miRNAs downregulate TP53I11, a key tumor suppressor that regulates ER Ca2+ levels." (PMID 39795889, 2024). "Hypoxia-induced miR-210 can regulate tumor cell susceptibility to cytolytic T-lymphocyte-mediated lysis by a mechanism involving its downstream targets PTPN1, HOXA1, and TP53I11." (PMID 29872497, 2018). "Additionally, our data indicate that TP53I11 expression in primary tumours correlates with overall survival, while high RAD51 expression is linked to worse outcomes due to its role in HR and genomic instability." (PMID 41007296, 2025). "Interestingly, TP53I11 expression was upregulated in cells treated with the anti-tumor agent curcumin, further supporting its role as a tumor suppressor in HCC." (PMID 39795889, 2024). "Interestingly, our findings reveal that the 10 ER-Ca2+-lowering miRNAs target the tumor suppressor TP53I11, potentially positioning these miRNAs as tumor promoters." (PMID 39795889, 2024). "TP53I11 was found to promote apoptosis by binding to DNA as well as inhibit tumor metastasis." (PMID 34916903, 2021). "We also identified two other genes (TP53I11 and CDKL1) that contain tumor-specific repeat instabilities in their exons, and where repeat instability had not been documented so far." (PMID 26376692, 2015).
cancer (5 papers, 2014 to 2024). A tumor composed of atypical neoplastic, often pleomorphic cells that invade other tissues. "We used HeLa cells, a well-characterized cancer cell line, to examine how TP53I11 affects ER Ca2+ homeostasis using Ca2+ imaging." (PMID 39795889, 2024). "Functional assays confirmed that TP53I11 influences ER Ca2+ levels and affects cancer cell proliferation." (PMID 39795889, 2024). "Furthermore, we discovered that chemotherapeutic agent doxorubicin (DOX) can upregulate TP53I11, resulting in elevated ER Ca2+ levels in cancer cells." (PMID 39795889, 2024). "Importantly, our function assays confirm that TP53I11 plays a critical role in influencing ER Ca2+ levels, thereby affecting cancer cell proliferation." (PMID 39795889, 2024). "To explore this, we investigated whether TP53I11 might impact cancer progression by elevating ER Ca2+ levels." (PMID 39795889, 2024). "Our findings suggest that modulating TP53I11 expression and ER Ca2+ levels may offer therapeutic avenues for cancer therapy." (PMID 39795889, 2024). "The observed upregulation of TP53I11 in response to DOX, along with increased ER Ca2+ levels and reduced cell proliferation, suggests that TP53I11 plays a crucial role in mediating the effects of DOX on cancer cell proliferation, likely through its capacity to elevate ER Ca2+ levels." (PMID 39795889, 2024). "Additionally, TP53I11 modulates ER Ca2+ levels and cancer cell growth during chemotherapy, particularly with doxorubicin (DOX), which upregulates TP53I11 and enhances ER Ca2+ accumulation." (PMID 39795889, 2024). "Our findings also highlight the role of TP53I11 in modulating cancer cell proliferation." (PMID 39795889, 2024). "Additionally, DOX treatment significantly increases TP53I11 expression, suggesting that TP53I11 may contribute to the anti-cancer effects of DOX." (PMID 39795889, 2024). "TP53I11 inhibits the epithelial-mesenchymal transition (EMT) of BC cells, preventing cancer metastasis." (PMID 36685904, 2022).
TP53I11 also shares sentences with these, for which no sentence is quoted: glioblastoma (3 papers); glioma (1); varicocele (1).